CSNK2B (casein kinase 2 beta)
Diseases named in the same sentence as CSNK2B in open-access papers (continued):
Sharing a sentence is not in itself a finding about the gene and the disease.
colon cancer (1 paper, 2023). "We also confirmed through experiments that two C-to-U RESs in CSNK2B or RPS14 had different effects on colon cancer cells." (PMID 36969056, 2023). "Importantly, we experimentally validated two C-to-U RESs, in CSNK2B (casein kinase II beta subunit) and RPS14 (ribosomal protein S14), respectively, with different impacts on cell proliferation in colon cancer." (PMID 36969056, 2023).
Filippi syndrome (1 paper, 2022). Filippi syndrome is characterized by microcephaly, cutaneous syndactyly of the fingers and toes, intellectual deficit, growth retardation and a characteristic facies (high and broad nasal bridge, thin alae nasi, micrognathia and a high frontal hairline). "The clinical characterization of patients with pathogenic variants in CSNK2B who display overlap with clinical Filippi syndrome provides evidence toward genetic heterogeneity." (PMID 35571680, 2022).
Jeavons syndrome (1 paper, 2025). "In this study, we identified a novel CSNK2B mutation in a pediatric patient presenting with Jeavons syndrome features." (PMID 40969926, 2025). "In this study, we identified a novel CSNK2B heterozygous mutation NM_001320.7:c.268A > C (p.Thr90Pro) in a child with Jeavons syndrome, classified as a likely pathogenic under ACMG guidelines." (PMID 40969926, 2025). "This pathogenic mutation enriches the spectrum of CSNK2B gene mutations and suggests that CSNK2B may be a causative gene for Jeavons syndrome." (PMID 40969926, 2025). "This phenotypic overlap, combined with CSNK2B's established neurodevelopmental functions, positions CSNK2B as a novel candidate gene for Jeavons syndrome." (PMID 40969926, 2025).
liver cancer (1 paper, 2020). An epithelial or non-epithelial malignant neoplasm that arises from the liver. "The CKB2 ortholog, CSNK2B, is over-expressed in several liver cancers and therapeutics are currently in clinical trial." (PMID 32994210, 2020).
lymphoid tumors (1 paper, 2015). "GEP of the available study confirmed the trend of the immunohistochemical results, with high CSNK2A1, CSNK2A2 and CSNK2B mRNA levels in all the considered lymphoid tumors." (PMID 25788269, 2015).
meningioma (1 paper, 2024). A generally slow growing tumor attached to the dura mater. "In our study, inhibiting RACK1 and CSNK2B expression significantly suppressed the proliferation and migration ability of meningioma cells." (PMID 38398158, 2024). "Initially, we found that HA inhibits CSNK2B protein expression in meningioma cells in a dose-dependent manner, as shown by Western blot analysis." (PMID 38398158, 2024). "To investigate the effect of CSNK2B on the behavior of meningioma cells, we altered the expression of RACK1 and CSNK2B in IOMM-LEE and CH157-MN cells." (PMID 38398158, 2024). "Then, using cycloheximide (CHX) to inhibit protein synthesis, we observed by Western blot that CSNK2B degradation was significantly accelerated in meningioma cells with RACK1 knockdown, whereas degradation was significantly slowed in those cells overexpressing RACK1." (PMID 38398158, 2024). "Furthermore, flow cytometry revealed that CSNK2B knockdown attenuated the effects of RACK1 overexpression on the meningioma cell cycle." (PMID 38398158, 2024). "However, the role of CSNK2B in the context of meningiomas has yet to be demonstrated." (PMID 38398158, 2024). "Our study found that in malignant meningioma cells, RACK1 interacts with CSNK2B and inhibits its ubiquitination and degradation by binding to it." (PMID 38398158, 2024). "We discovered a positive correlation between meningioma malignancy and the levels of the receptor for activated C kinase 1 (RACK1), which interacts with CSNK2B, the β subunit of casein kinase 2 (CK2), inhibiting its ubiquitination and subsequent degradation." (PMID 38398158, 2024). "RACK1 and CSNK2B have been shown to promote tumor progression but their roles in meningiomas are not clear." (PMID 38398158, 2024). "Additionally, the subcutaneous implantation of tumors in nude mice showed that, compared to the control group, meningioma cells with RACK1 knockdown formed smaller tumors, while those overexpressing CSNK2B developed larger tumors." (PMID 38398158, 2024).
Monge’s disease (1 paper, 2023). "We also prove, for what we believe is the first time, that the lncRNA HIKER/LINC02228 regulates the excessive erythropoiesis of Monge’s disease and that its action is mediated through CSNK2B, a casein kinase." (PMID 37022795, 2023). "Indeed, we detected decreased expression of EPOR (a downstream target of HIF-1) following CSNK2B KD, suggesting that, in addition to GATA1, HIF signaling might be another potential mechanism underlying the role of CSNK2B in excessive erythropoiesis in Monge’s disease." (PMID 37022795, 2023).
myoclonic epilepsy (1 paper, 2019). A group of epilepsy syndromes in which myoclonic seizures are a prominent feature. "Then, a study reported a truncating mutation in CSNK2B (c.108dup) that causes myoclonic epilepsy and ID21." (PMID 31784560, 2019).
prostate carcinoma (1 paper, 2021). A carcinoma that arises from epithelial cells of the prostate gland. "CSNK2A and CSNK2B, which both were found significantly up-regulated, are subunits of the protein kinase CK2 (CSNK2), which has been associated with various cancer types, such as breast, lung, colon, and prostate cancer." (PMID 34227026, 2021).
Rickettsia infection (1 paper, 2011). "On the basis of comparative analyses, we predicted that the activity of RickA, a Rickettsia protein shown to activate the ARP2/3 complex in vitro, would also be regulated by CSNK2B upon Rickettsia infection." (PMID 21853127, 2011).
sarcoidosis (1 paper, 2025). Sarcoidosis is a multisystemic disorder of unknown cause characterized by the formation of immune granulomas in involved organs. "The OR of sarcoidosis ranged from 0.02 (95% CI 0.00, 0.16) to 6.89 (95% CI 5.23,9.08) per SD increase in genetically predicted levels of protein CSNK2B and AIF1, respectively." (PMID 40075078, 2025).
systemic lupus erythematosus (1 paper, 2020). An autoimmune multi-organ disease typically associated with vasculopathy and autoantibody production. "In the third trimester, systemic lupus erythematosus and proteasome were enriched in the acute disease while Fc gamma R-mediated phagocytosis (VAV1, MARCKSL1, WASF2, DNM2, HCK, MAP2K1 genes) and adherens junction (ACTG1, WASF2, SMAD4, CSNK2B, EP300 genes) represented the subclinical category." (PMID 32012176, 2020).
cancer (12 papers, 2016 to 2025). A tumor composed of atypical neoplastic, often pleomorphic cells that invade other tissues. "We also observed that HDAC8 expression was positively correlated with CSNK2A1, CSNK2A2, and CSNK2B in multiple cancer types in public databases." (PMID 40013761, 2025). "We introduced wild-type CSNK2B cDNA and mutant CSNK2B_T213M cDNA into HCT116 cells in order to prove that editing CSNK2B can cause cancer." (PMID 36969056, 2023). "We also analyzed the correlation between CSNK2B expression and HDAC family‐related genes in the TIMER2.0 public database of multi‐cancer, and we found that the expression of CSNK2B showed a positive correlation with HDAC1, HADC2, HDAC5, HDAC6, and HDAC8 in LUAD and LUSC." (PMID 40013761, 2025). "CSNK2B promotes cell regulation by activating the mTOR signaling pathway in cancers." (PMID 40700255, 2025). "Our data also reveals the downregulation of casein kinase II subunit beta (CK2b; CSNK2B), a kinase whose upregulation is known to evade senescence and promote cancer progression." (PMID 38216124, 2024). "Our findings indicate that the expression levels of CSNK2B, MTERF3, and PGAM5 are elevated in multiple cancers, while the expression levels of PINK1 and PRKN are reduced in several cancers." (PMID 38913914, 2024). "By incorporating the weak genes CSNK2B, HLA-A, HLA-C, and HLA-DRA, the PD-1, PD-L1 cancer immunotherapy pathway was significantly enriched." (PMID 37065470, 2023). "We observed an upregulation of CTNNB1 and other genes involved in CTNNB1 stabilization (CSNK2A1, CSNK2B, DVL2, DVL3,) in rHGP cancer areas." (PMID 36691028, 2023).
tumor (12 papers, 2015 to 2025). "Since tumor tissues predominantly consisted of tumor cells, any potential impact of CSNK2B expression specifically in NSCLC tumor cells on patient prognosis was eliminated." (PMID 40013761, 2025). "This shows a potential tumor selective vulnerability that can be exploited in PDAC or a subset of PDAC patients since CSNK2A1/3 and CSNK2B were top features in only one of the tumor cell models, P0422-T1." (PMID 39221276, 2024). "We discovered that altered CSNK2B T213M considerably increased cell viability relative to wild-type CSNK2B, implying that edited CSNK2B can contribute significantly to tumor proliferation." (PMID 36969056, 2023). "In sharp contrast, CSNK2B-knockdown tumors exhibited a markedly tumor growth rate than the control cells." (PMID 33928514, 2021). "Besides, in previous studies, CSNK2B has been shown to affect tumor progression by activating the NF-κB pathway." (PMID 38398158, 2024). "In addition, NELFE, β-catenin and CSNK2B were all remarkably upregulated in tumor tissues compared with adjacent normal tissues, and their expression levels in GC were positively correlated with each other." (PMID 33526068, 2021). "Similarly, high CSNK2B expression was also found in tumor tissues when compared with adjacent normal tissues (P < 0.05)." (PMID 33526068, 2021). "In summary, we identified CSNK2B as an oncogene in CRC, which promotes tumor cell proliferation in vitro and in vivo by activating the mTOR signaling pathway." (PMID 33928514, 2021). "Several studies have reported the individual expression pattern and function of each hub (TK1, CSNK2B, VIM, YWHAB and HSP90AB1) in different tumors and tumor models in vitro." (PMID 27527857, 2016). "Concerning the genes related to tumor progression, we found HSP90AB1, GRB2, ERBB2/3, EIF4A3, HDGF, and CSNK2B." (PMID 25625699, 2015). "This suggests that CSNK2B expression in tumor tissues does not significantly affect the survival of patients with NSCLC." (PMID 40013761, 2025).
neurodevelopmental disorder (9 papers, 2018 to 2026). A behavioral and cognitive disorder with onset during the developmental period that involves impaired or aberrant development of intellectual, motor, or social functions. "Mutation or disruption of ALMS1 and CSNK2B lead to severe neurodevelopmental disorder, indicating these two genes are essential for neurodevelopment." (PMID 29483533, 2018). "A comprehensive molecular docking analysis was conducted to characterize the binding interactions between selected natural compounds and three pivotal protein targets implicated in neurodevelopmental disorders: CSNK2B (PDB ID 3EED), GRIN1 (PDB ID 5H8H), and MAPK1 (PDB ID 6SLG)." (PMID 41009441, 2025). "POBINDS is a rare neurodevelopmental disorder related to loss-of-function mutations of CSNK2B." (PMID 35205321, 2022). "Recently, mutations in CSNK2A1 and CSNK2B genes, encoding for α catalytic subunit and β regulatory subunits, respectively, have been found in patients with neurodevelopmental disorders (NDDs), but the functional role of CK2 has not been elucidated in these works." (PMID 31779225, 2019). "Interestingly, mutations in CSNK2A1 and CSNK2B have been found in patients affected by neurodevelopmental disorders (NDDs), which combine intellectual disability, autism spectrum disorder, and general developmental delay." (PMID 31779225, 2019).
infection (7 papers, 2011 to 2023). The state of being infected such as from the introduction of a foreign agent such as serum, vaccine, antigenic substance or organism. "EgPSC infection also caused the upregulation of Cgn, Epb41, Cldn8, Shroom3, Cask, Rab3b, Epb41l2, Csnk2b, Prkcb, and MyI12a." (PMID 36713407, 2022). "Because the absence of the important antiviral effector, PLAAT4, in rodents precluded use of a mouse infection model, we examined the impact of silencing CSNK2B expression on HAV replication in primary human hepatocytes (PHHs)." (PMID 37094077, 2023). "We next analyzed R. conorii spread in CSNK1A1-, CSNK2B-depleted cells and determined that the infection foci formed in the corresponding cells were indistinguishable from the ones observed in wild-type cells." (PMID 21853127, 2011). "Moreover, DLD-1 and SW620 with stable knockdown of CSNK2B using lentiviral infection of shRNA were established, and concordant results were observed in colony formation assays." (PMID 33928514, 2021).
neurologic disorder (2 papers, 2022). "Poirier–Bienvenu neurodevelopmental syndrome is a neurologic disorder caused by mutations in the CSNK2B gene." (PMID 34983633, 2022).
CSNK2B also shares sentences with these, for which no sentence is quoted: developmental delay (5 papers); colorectal cancer (3); major depression (2); psychiatric disorder (2); Alzheimer disease (1); anemia (1); autosomal recessive spastic paraplegia-86 (1); bipolar disorder (1); cataract (1); common variable immunodeficiency (1); Dravet syndrome (1); early-onset epilepsy (1); frequent infections (1); lung adenocarcinoma (1); lung squamous cell carcinoma (1); mesothelioma (1); mucopolysaccharidosis type 2 (1); myoclonic seizures (1); myopia (1); neurodegenerative disease (1); Obesity (1); pancreatic cancer (1); renal cell carcinoma (1); sarcopenia (1); Spastic paraplegia (1); tauopathy (1); X-linked myotubular myopathy (1).